GMCL1 (germ cell-less 1, spermatogenesis associated)
Description:
Possible function in spermatogenesis.
Synonyms: BTBD13; GCL; SPATA29; FLJ13057; GCL1
Tractability: PROTAC: ubiquitination databases record sites on it.
Gene: Protein-coding gene on chromosome 2 (69,829,646 to 69,881,384, forward strand). Ensembl gene ENSG00000087338.
Subcellular location: Nucleus matrix
Gene Ontology:
Molecular function: identical protein binding; protein binding
Biological process: germ cell development
Cellular component: nucleus; nuclear matrix
Genetic constraint (gnomAD): Loss-of-function variants: 21 observed, 20.4 expected, observed/expected ratio (o/e) 1.03, 90% interval 0.73 to 1.48. The upper end of that interval is the gene's LOEUF score, 1.48, which puts it in group 6 of 6, group 1 being the genes least tolerant of losing a copy. Missense variants: 242 observed, 227.2 expected, observed/expected ratio (o/e) 1.07, 90% interval 0.96 to 1.18. Synonymous variants: 106 observed, 86.31 expected, observed/expected ratio (o/e) 1.23, 90% interval 1.05 to 1.44.
Homologues: Orthologues: chimpanzee GMCL1 (99% identical), macaque GMCL1 (99% identical), dog GMCL1 (92% identical), rat Gmcl1 (91% identical), mouse Gmcl1 (90% identical), tropical clawed frog gmcl1 (75% identical), zebrafish gmcl1 (70% identical), Drosophila melanogaster gcl (34% identical), Caenorhabditis elegans gcl-1 (27% identical). Paralogues in human: GMCL2 (91% identical), BTBD16 (20% identical), C10orf120 (11% identical).
Diseases named in the same sentence as GMCL1 in open-access papers:
GMCL1 is named in the same sentence as 10 diseases in open-access papers, as found by Europe PMC text mining. Sharing a sentence is not in itself a finding about the gene and the disease. The quoted sentences say what the papers report.
lung carcinoma (2 papers, 2025 to 2026).
asthenozoospermia (1 paper, 2026). "The role of GMCL1 in germ cell development appears to have been evolutionarily conserved as loss of GMCL1 expression in mice has been shown to cause defects in meiosis and spermiogenesis, and altered GMCL1 expression was functionally associated with human asthenozoospermia." (PMID 41553759, 2026).
multiple sclerosis (1 paper, 2021). A progressive autoimmune disorder affecting the central nervous system resulting in demyelination. "The obtained results revealed that only the SARS-CoV-2 peptide, which matches with the GMCL1 gene name, could be associated with Multiple sclerosis and Rheumatoid arthritis." (PMID 34447375, 2021).
stomach cancers (1 paper, 2025). "Cancer database analysis reveals that GMCL1 is overexpressed in multiple cancers, including bladder, brain, breast, kidney, liver, lung, ovary, prostate, skin, and stomach cancers." (PMID 40166203, 2025).
cancer (2 papers, 2025 to 2026). A tumor composed of atypical neoplastic, often pleomorphic cells that invade other tissues. "Given our finding that GMCL1 controls 53BP1 stability during prolonged mitosis, we sought to investigate whether GMCL1 expression is associated with taxane resistance and 53BP1 protein abundance in cancer cells." (PMID 41553759, 2026). "Germ cell-less protein-like 1 (GMCL1) expression shows positive correlation with taxane resistance in cancer cell lines." (PMID 41553759, 2026). "To assess the clinical significance of GMCL1, we investigated the relationship between GMCL1 expression levels and Taxol resistance in various cancer cell lines." (PMID 40166203, 2025). "Finally, our results indicate that GMCL1 inhibition represents a novel strategy to restore taxane sensitivity in resistant cancers." (PMID 40166203, 2025). "Interestingly, we found that several cancer types (e.g.: endometrial, breast, and upper aerodigestive tract cancers) with high levels of GMCL1 mRNA exhibited resistance to paclitaxel, cabazitaxel, and/or docetaxel." (PMID 40166203, 2025). "(A) Schematic overview of DepMap and PRISM data integration used in the analysis, including GMCL1 mRNA (protein not available) and drug response for taxanes across DepMap cancer cell lines." (PMID 41553759, 2026).
tumor (2 papers, 2025 to 2026). "This underscores the role of GMCL1 in mitotic regulation and chromosome stability, which may vary based on tumor type, genetic background, and additional oncogenic mutations." (PMID 41553759, 2026). "This underscores GMCL1’s role in mitotic regulation and genomic stability, which may vary based on tumor type, genetic background, and additional oncogenic mutations." (PMID 40166203, 2025).
neurodegenerative disease (1 paper, 2023). A disorder of the central nervous system characterized by gradual and progressive loss of neural tissue and neurologic function. "The miR-124-3p enriched for three hubs (Gmcl1, Snx24, and Eif3l) of those modules negatively correlated with the HNS group and enriched for inflammatory pathways or neurodegenerative diseases." (PMID 37355705, 2023).
GMCL1 also shares sentences with these, for which no sentence is quoted: male fertility (1 paper); male infertility (1); rheumatoid arthritis (1).